CHEK1 (checkpoint kinase 1)
Diseases named in the same sentence as CHEK1 in open-access papers (continued):
Sharing a sentence is not in itself a finding about the gene and the disease.
Ewing sarcoma (8 papers, 2017 to 2025). A small round cell tumor that lacks morphologic, immunohistochemical, and electron microscopic evidence of neuroectodermal differentiation. "Treatment of Ewing sarcoma cells with gemcitabine also results in activation of checkpoint kinase 1 (CHK1), which is a critical mediator of cell survival in the setting of impaired DNA replication." (PMID 29152060, 2017). "Moreover, we also found that inhibition of checkpoint kinase 1 (CHK1), the major regulator of the response to impaired DNA replication, significantly increases the toxicity of gemcitabine in Ewing sarcoma cells both in vitro and in vivo." (PMID 29152060, 2017).
squamous cell carcinoma (8 papers, 2015 to 2026). A carcinoma arising from squamous epithelial cells. "The expression of CHEK1 can be regulated by miR-195 in cardiomyocytes and human epidermoid carcinoma cell line reported by two groups respectively." (PMID 25840419, 2015). "CHEK1 transcripts were significantly up-regulated in SCLC tumors with a median increase of 2-fold (1.7-fold) and 5-fold (4.6-fold), compared to adenocarcinomas and squamous cell carcinomas, respectively (p < 0.0001)." (PMID 29138515, 2017).
anemia (7 papers, 2010 to 2025). A reduction in the number of red blood cells, the amount of hemoglobin, and/or the volume of packed red blood cells. "Checkpoint Kinase 1 (Chk1) is best known for its role in the cell cycle and DNA damage pathways, and it has been shown to play a part in several pathways which when disrupted can lead to anemia." (PMID 20052416, 2010). "Notably, proteins decreased only after both combination treatments include proteins involved in the DNA damage response (DDR) like BRAT1, Fanconi Anemia Complementation Group I (FANCI) and CHEK1, indicating that the cells might be more prone to DNA damage." (PMID 30871073, 2019).
acute leukemia (6 papers, 2015 to 2025). A clonal (malignant) hematopoietic disorder with an acute onset, affecting the bone marrow and the peripheral blood. "Increased PKR expression promotes genome instability in acute leukemia, and doxorubicin induces the phosphorylation of checkpoint kinase 1 (CHK1), which functions in the checkpoint response process." (PMID 36555509, 2022).
mesothelioma (6 papers, 2012 to 2025). A usually malignant and aggressive neoplasm of the mesothelium which is often associated with exposure to asbestos. "We also found previously unrecognised deletions in RB1 in 26% of cases and show sub-micromolar responses to downstream PLK1, CHEK1 and Aurora Kinase inhibitors in primary mesothelioma cells." (PMID 34580349, 2021). "After mesothelioma, ES were the solid tumors showing the highest levels of CHEK1 mRNA from the CCLE dataset." (PMID 27577084, 2016). "CHEK1 appears as a very important gene in resistance towards several DNA-damaging agents, and could be a promising marker for pemetrexed-platinum response and survival in mesothelioma." (PMID 22905093, 2012).
ovarian tumors (6 papers, 2013 to 2024). "Although our results do not elucidate whether CHEK1 acts more like an oncogene or suppressor in ovarian tumors, further investigation of its variants appears interesting in the context of potential targeted therapies with Prexasertib, a selective CHEK1 inhibitor." (PMID 39456660, 2024). "Using survival analysis, we also report that the set of three genes, CHEK1, AR, and LYN, can be used in the prognosis of ovarian tumors." (PMID 23383610, 2013). "We report three genes (IRAK1, CHEK1 and BUB1) to be significant in ovarian tumor samples for the first time, to the best of our knowledge." (PMID 23383610, 2013).
chronic lymphocytic leukemia (5 papers, 2015 to 2023). "Furthermore, by integrating a newly generated drug screening dataset on primary tumor samples, we discovered a previously unreported survival dependence on Checkpoint kinase 1 (CHEK1) by a molecular subgroup of chronic lymphocytic leukemia samples, highlighting the clinical potential of our method." (PMID 35994503, 2022).
invasive breast carcinoma (5 papers, 2017 to 2024). A carcinoma that infiltrates the breast parenchyma. "High expression of RNF126 is an independent predictor of poor prognosis in invasive breast cancer and is considered a potential biomarker for cancer responsiveness to checkpoint kinase 1 (CHK1) inhibitors." (PMID 32131492, 2020). "In particular, a statistically significant association was found between CHEK1, MAP2K1, and PLK1 overexpression and worse overall survival in breast invasive carcinoma patients, indicated by pooled hazard ratio (HR) values higher than 1 and p-values lower than 0.05." (PMID 33898418, 2021). "The results of the boxplot analysis indicated overexpression of CHEK1 and PLK1 in breast invasive carcinoma compared to healthy controls, aligning with our findings." (PMID 39473450, 2024). "Notably, protein–protein interaction (PPI) network analysis identified CHEK1 and PLK1 as central hub genes with overexpression correlating with poor prognosis in invasive breast carcinoma." (PMID 39473450, 2024).
lung squamous cell carcinoma (5 papers, 2016 to 2026). "Previous studies have demonstrated that miR‐139‐3p was downregulated in lung squamous cell carcinoma tissues and that checkpoint kinase 1 (CHEK1) could be targeted by miR‐139‐3p." (PMID 37517032, 2023). "Moreover, the expression of checkpoint kinase 1 (CHEK1) was regulated directly by miR-139-3p in lung squamous cell carcinoma cells." (PMID 38067275, 2023).
Telangiectasia (5 papers, 2013 to 2023). Telangiectasias refer to small dilated blood vessels located near the surface of the skin or mucous membranes, measuring between 0.5 and 1 millimeter in diameter.
lymphoid tumors (4 papers, 2007 to 2025). "The checkpoint kinase-1 (Chk1) is also lost in aggressive lymphoid tumors." (PMID 18159231, 2007).
myeloid leukemia (4 papers, 2019 to 2022). A clonal proliferation of myeloid cells and their precursors in the bone marrow, peripheral blood, and spleen. "Our recent studies demonstrated that pyrimidine synthesis inhibitors induce differentiation of myeloid leukemia by activating the ataxia telangiectasia and Rad3-related (ATR)/checkpoint kinase 1 (Chk1) DNA damage signaling pathway via pyrimidine depletion." (PMID 35790845, 2022). "We have previously reported that 5-aminoimidazole-4-carboxamide ribonucleoside (AICAr) and brequinar, a DHODH inhibitor, induced differentiation of myeloid leukemia by activating the ataxia telangiectasia and Rad3-related (ATR)/checkpoint kinase 1 (Chk1) via pyrimidine depletion." (PMID 35790845, 2022).
oral cancer (4 papers, 2019 to 2025). "Next, we analyzed the expression levels of these same genes in array data of 22 paired HPV-negative oral cancers and oral mucosa to investigate changed expression in malignant cells, and showed a highly significant 2.7-fold upregulation of CHEK1 mRNA in cancers as compared to oral mucosa." (PMID 31209198, 2019).
pancreatic ductal adenocarcinoma (4 papers, 2021 to 2024). An infiltrating adenocarcinoma that arises from the epithelial cells of the pancreas.
thyroid cancer (4 papers, 2015 to 2024). "The expression levels of CHEK1, c-KIT, SLC26A4, TG and TPO were significantly altered in all types of thyroid carcinomas." (PMID 27329729, 2016).
colorectal tumor (3 papers, 2020 to 2025). "The ATR, CHEK1 and CDC7 synthetic lethal effects can be replicated using small molecule inhibitors and in addition, the CDC7 dependency of colorectal tumour cell lines with reduced FBXW7 mRNA expression in the DepMap dataset was seen." (PMID 37866880, 2024).
diabetes (3 papers, 2019 to 2024). "Although direct evidence on CHEK1 and DR risk is unreported, DNA damage repair mechanisms have been implicated in diabetes and its complications." (PMID 39199149, 2024). "In summary, this SMR analysis explored the potential causal effects of OS-related genes on diabetes and its microvascular complications, highlighting the significant roles of TP53INP1, CHEK1, SUOX, and ICAM1 in the pathogenesis." (PMID 39199149, 2024).
esophageal cancer (3 papers, 2018 to 2025). A primary or metastatic malignant neoplasm involving the esophagus. "In protein–protein interactions, one study suggested that the relationship between RAD51 and autophagy is associated with checkpoint kinase 1 (CHK1) in an esophageal cancer model by inhibiting autophagy." (PMID 34067336, 2021). "Ginsenoside Ro has been shown to enhance 5-fluorouracil sensitivity in esophageal cancer by disrupting autophagic flux through the ESR2-NCF1-ROS pathway, leading to CHEK1-mediated DNA damage activation." (PMID 41208974, 2025).
esophageal squamous cell carcinoma (3 papers, 2024). Esophageal squamous cell carcinoma (ESCC) is a type of esophageal carcinoma (EC) that can affect any part of the esophagus, but is usually located in the upper or middle third. "The ncRNA activated by DNA damage was also found to activate ATR/checkpoint kinase 1 (Chk1) signaling pathway to promote radioresistance in esophageal squamous cell carcinoma." (PMID 39055884, 2024).
Gynecologic Cancer (3 papers, 2012 to 2024). "Although no overt oncogenic potential in endometriotic tissue was observed, expressions of a few genes (CHEK1, ERBB family, laminin gamma and Ki-67) associated with gynecological cancers were seen to be up-regulated." (PMID 23006437, 2012). "The ataxia telangiectasia and Rad3-related (ATR) inhibitors, DNA-dependent protein kinase (DNA-PK) inhibitors, WEE1 inhibitors, and checkpoint kinase 1/2 (CHK1/2) inhibitors have shown promising clinical results recently, and a number of ongoing trials are focusing on gynecologic cancers." (PMID 34680987, 2021).
lymph node metastasis (3 papers, 2023 to 2026). "DCAF8 decrease was also marginally associated (p = 0.06) with distal lymph node metastasis, while CHEK1 and PAX8 expressions were significantly correlated with worse overall patients’ survival (p < 0.0001 and p < 0.049, respectively), as evidenced by the relevant Kaplan–Meier curves." (PMID 36831395, 2023).
malignant glioma (3 papers, 2017 to 2023). A grade III or grade IV glioma arising from the central nervous system. "Checkpoint Kinase 1 (CHEK1), the essential cell cycle checkpoint regulating gene, was significantly down-regulated by ATRX deficiency in numerous high-grade glioma (HGG) models, resulting in the early release of G2/M entry following irradiation." (PMID 37190157, 2023).
clear cell carcinoma (2 papers, 2018 to 2023). "Recent studies suggest that this CHEK1 variant is extremely common in primary and recurrent HGSOC, but undetectable in a clear-cell carcinoma subtype of EOC." (PMID 37048111, 2023).
female infertility (2 papers, 2024 to 2025). Diminished or absent ability of a female to achieve conception. "Our previous report found that the maternal mutation in CHEK1 leads to mitotic arrest in human zygotes thus resulting in female infertility." (PMID 40533835, 2025). "Our previous study demonstrated that gain-of-function mutations of CHEK1 lead to the failure of zygote cleavage and subsequent female infertility." (PMID 40533835, 2025).
ovarian clear cell cancer (2 papers, 2018 to 2024). An invasive malignant neoplasm that arises from the ovary and is characterized by a predominance of clear and hobnail malignant epithelial cells. "Transcription factor hepatocyte nuclear factor 1-beta (HNF-1β) enhances checkpoint kinase 1 (Chk1) activation and promotes G2/M cell cycle progression in ovarian clear cell carcinoma (CCC) following exposure to diverse genotoxic agents including bleomycin." (PMID 29707125, 2018).
pancreatic adenocarcinoma (2 papers, 2016 to 2026). "These databases corroborated our findings, indicating a pronounced upregulation of CHEK1 expression in pancreatic adenocarcinoma (PAAD) tissues relative to normal controls." (PMID 41564103, 2026).
pituitary tumor (2 papers, 2020 to 2024). A benign or malignant neoplasm affecting the pituitary gland.
seminoma (2 papers, 2020 to 2025). A radiosensitive malignant germ cell tumor found in the testis (especially undescended), and extragonadal sites (anterior mediastinum and pineal gland). "Interestingly, CDK6 was amplified in 2.6% of seminomas, while CCND3 (CyclinD3; 1.7%) and CHEK1 (6.8%) were amplified or deleted in non-seminomas, respectively." (PMID 32418994, 2020). "For example, seminomas showed significantly higher frequency of 11q24.2 (CHEK1/CBL) deletions compared to non-seminomas (30% vs. 11%; Fisher’s exact test, P = 3.41e-04)." (PMID 40568177, 2025).
skin cancer (2 papers, 2017 to 2025). "Since ATR seems to exhibit dual roles in different skin cancers, it is imperative to delineate the exact interaction between PLK4 and ATR/CHEK1 pathways." (PMID 40940791, 2025). "Additionally that UV affects the ATR/CHEK1 pathway, it would be interesting to study UV-mediated dysregulation of PLK4/ATR/CHEK1 axis in skin cancer models." (PMID 40940791, 2025).
soft tissue sarcoma (2 papers, 2020 to 2025). A malignant neoplasm arising from muscle tissue, adipose tissue, blood vessels, fibrous tissue, or other supportive tissues excluding the bones. "In soft tissue sarcomas, CHEK1 serves as an unfavorable prognostic biomarker associated with immunosuppressive phenotypes, showing significant overexpression in immune-low tumors and correlating with altered patterns of tumor-infiltrating immune cells." (PMID 41208974, 2025).
T cell lymphomas (2 papers, 2017 to 2019). "The authors’ conclusion was that CHEK1, as well as Myc, work as targets for ixazomib in cancer, and chemotherapy protocols including anti-CHEK1 drugs may represent a new approach for T-cell lymphoma therapy." (PMID 31497245, 2019).
Bloom syndrome (1 paper, 2025). Bloom syndrome (BSyn) is a rare chromosomal breakage syndrome characterized by a marked genetic instability associated with pre- and postnatal growth retardation, facial sun-sensitive telangiectatic erythema, increased susceptibility to infections, and predisposition to cancer. "Elevated expression of KLF5 promotes the expression of key HRR pathway genes, including RAD51, checkpoint kinase 1 (CHEK1), RAD54 like (RAD54L), essential meiotic structure-specific endonuclease 1 (EME1), and Bloom syndrome (BLM), thereby reversing the HRR suppression mediated by PARPi." (PMID 40032852, 2025).
chondrosarcoma (1 paper, 2020). A malignant cartilaginous matrix-producing mesenchymal neoplasm arising from the bone and soft tissue. "We have previously shown that targeting cell cycle regulators, especially Checkpoint Kinase 1 (CHK1), could be a promising therapeutic strategy for chondrosarcoma patients." (PMID 33266275, 2020).
COVID-19 (1 paper, 2021). A disease caused by infection with severe acute respiratory syndrome coronavirus 2. "CHEK1, which is a gene that is necessary for responding to DNA damage, was reported to be a potential target of saikosaponins which might function as an adjuvant therapy for COVID-19 patients." (PMID 34917088, 2021).
diabetic retinopathy (1 paper, 2024). "Significantly, two other candidate genes, SUOX and CHEK1, which had not been intensively studied, were identified with a putative causal relationship with diabetic retinopathy." (PMID 39199149, 2024). "Similarly, an inverse association was observed between gene methylation and expression in CHEK1 (cg07110182), confirming the beneficial effect of modification of CHEK1 by cg07110182 in diabetic retinopathy." (PMID 39199149, 2024). "Similarly, an inverse association was observed with respect to gene methylation and expression in CHEK1 (cg07110182), confirming the negative effect of CHEK1 expression in diabetic retinopathy (OR 2.21, 95%CI 1.42–3.44)." (PMID 39199149, 2024).
endometrial tumors (1 paper, 2024). "The CHEK1 mRNA expression level was elevated in both groups of endometrial tumors compared to KRAS and ATR mRNA expression levels." (PMID 38669256, 2024).
epilepsy (1 paper, 2025). A brain disorder characterized by episodes of abnormally increased neuronal discharge resulting in transient episodes of sensory or motor neurological dysfunction, or psychic dysfunction. "In neurological disorders, aberrant isoforms of TRA2β have been linked to intellectual disability, epilepsy, and AD, via altered splicing of genes like CHEK1 and RAGE." (PMID 41009380, 2025).
gastric adenocarcinoma (1 paper, 2020). "The result shows that downregulation of CHEK1 expression in patients with gastric adenocarcinoma is associated with poor prognosis." (PMID 32178478, 2020).
Hepatitis B (1 paper, 2022).
hereditary ovarian cancer (1 paper, 2020). "CHEK1, involved in checkpoint mediated cell cycle arrest in response to e.g., DNA damage, has been reported to act as BRCA-like tumor suppressors when mutated in hereditary ovarian cancer." (PMID 32133296, 2020).
Li-Fraumeni syndrome (1 paper, 2019). "Interestingly, as CHEK1 is known as a DNA-damage response (DDR) coordinator, individuals carrying inactivated mutations in this gene are more susceptible to developing many types of cancer, as seen in Li Fraumeni syndrome patients." (PMID 31497245, 2019).
male infertility (1 paper, 2022). The inability of the male to effect fertilization of an ovum after a specified period of unprotected intercourse. "One proposed mechanism of action is that male infertility, as a result of abnormal spermatozoa, is caused by smoking-induced DNA damage due to activation of the checkpoint kinase 1 (Chk1) which facilitates S and G2 checkpoint arrest." (PMID 34536221, 2022).
metastatic melanoma (1 paper, 2021). A melanoma that has spread from its primary site to another anatomic site. "CYT-high metastatic melanomas had recurrent copy number amplifications in loci 1p12 (NOTCH2), 1q44 (OR2M4), 7q36.1 (KCNH2), 11q13.3 (FGF3/4), 12p11.23 (MED21) and 12q13.3 (R3HDM2) and deletions in 1p22.1 (RHOC, NRAS), 9p21.3 (CDKN2B), 10q23.2 (miR346), 11q23.3 (ATM, CHEK1, ETS1) and 15q15.3 (CASC4)." (PMID 33779796, 2021).
multinodular goiter (1 paper, 2015). Nodular goiter characterized by more than one discrete tissue mass. "Separate analysis of a subset of the multinodular goiter samples with more aggressive PTC subtypes revealed 2 - 4-fold upregulation in the levels of CHEK1, c-MET and TIMP1, and a 2-4-fold downregulation of BCL2, c-KIT, TG and PPARγ (lower part)." (PMID 25868389, 2015).